SLC7A11 (solute carrier family 7 member 11)
Diseases named in the same sentence as SLC7A11 in open-access papers (continued):
Sharing a sentence is not in itself a finding about the gene and the disease.
glioblastoma (70 papers, 2015 to 2026). The most malignant astrocytic tumor (WHO grade IV). "For instance, in glucose-deficient glioblastoma, heightened SLC7A11 expression leads to the generation of ROS and oxidative stress through the consumption of intracellular NADPH during the conversion of imported L-cystine to L-cysteine." (PMID 39040097, 2024). "Contrary to these observations, however, the overexpression of SLC7A11 induces cell death in glioblastomas under conditions of glucose deprivation caused by high-density cultivation." (PMID 37175751, 2023). "Expression of glutamate/cystine antiporter SLC7A11/xCT causing elevated extracellular glutamate in glioblastoma cells, promoting Tregs proliferation." (PMID 34095111, 2021). "Notably, a western blotting experiment indicated that SLC7A11 expression is associated with the sensitivity of glioblastomas to glucose deprivation." (PMID 38739940, 2024). "Sirtuin 3 (SIRT3) is the main mitochondrial deacetylase, and we previously demonstrated that targeting SIRT3 sensitized glioblastoma to ferroptosis by promoting mitophagy and inhibiting SLC7A11." (PMID 40298644, 2025). "Recently, SLC7A11 has been shown to be palmitoylated in glioblastomas, and this modification is required for the stability of SLC7A11." (PMID 40959280, 2025). "We previously demonstrated that targeted knockdown of SIRT3 sensitized glioblastoma to ferroptosis by promoting mitophagy and inhibiting SLC7A11." (PMID 40298644, 2025). "In glioblastoma, the S-palmitoylated modification of SLC7A11 is essential for its protein stabilization." (PMID 39624080, 2024). "For example, in glioblastoma cells starved for glucose, cystine uptake via xCT (with SLC7A11 as the catalytic subunit) leads to NADPH depletion, ROS accumulation, and cell death." (PMID 38685115, 2024). "Further studies revealed that glioblastoma cells with high SLC7A11 expression are sensitive to GLUT1 depletion." (PMID 38739940, 2024). "For instance, SLC7A11 was overexpressed in liver hepatocellular carcinoma (LIHC) but underexpressed in glioblastoma multiforme (GBM), which indicated that the mechanisms for disulfidoptosis in different cancer types were not the same." (PMID 38397869, 2024). "By contrast, studies have shown that in glioblastoma cells with high SLC7A11 activity, glucose metabolism can prevent the oxidative stress and cell death induced by SLC7A11-mediated cystine uptake." (PMID 38739940, 2024). "In the context of glioblastoma, for instance, glucose starvation can induce cell death more rapidly in cells with high SLC7A11 expression." (PMID 39040097, 2024). "S-palmytoylation diminishes ubiquitination of SLC7A11, thereby stabilizes and increases xCT levels, and provides increased resistance against ferroptosis in glioblastoma cells." (PMID 38908072, 2024). "It has been reported that mTOR activation increases SLC7A11 protein levels by suppressing lysosomal degradation in glioblastoma cells, and inhibition with Torin 1 reduced the protein levels of SLC7A11." (PMID 36856826, 2023). "Activated NF-κB inhibits ferroptosis in granulosa cells of polycystic ovary syndrome by upregulating the expression of GPX4, but which induces ferroptosis in glioblastoma by repression of SLC7A11." (PMID 37153794, 2023). "NKAP protects glioblastoma (GBM) cells from ferroptosis by upregulating SLC7A11 and promoting cell resistance to ferroptosis inducers." (PMID 37375731, 2023).
glioblastoma (continued). "The altered cancer metabolism through overexpression of SLC7A11 promotes immune evasion of glioblastoma multiforme (GBM) through dysfunction of T cell activation." (PMID 36552652, 2022). "Overexpression of SLC7A11 provides cancer stem cell-like properties to glioblastoma cells and is related to accelerated tumor growth and enhanced chemoresistance." (PMID 35280777, 2022). "We found that RSL3 led to an increase in lipid ROS concentration and downregulation of ferroptosis-related proteins such as GPX4, ATF4, and SLC7A11 (xCT) in glioblastoma cells." (PMID 34987700, 2021). "Primarily, glutamate is released by glioblastoma cells via cystine/glutamate antiporter solute carrier family 7 member 11 (SLC7A11 or xCT)." (PMID 34067762, 2021). "xCT, the protein encoded by SLC7A11, is a subunit of system xc-, and is upregulated in many cancer types, including NSCLC, triple-negative breast cancer, and glioblastomas." (PMID 33080927, 2020). "Overexpression of SLC7A11 resulted in decreased endogenous ROS levels as well as decreased migration and invasion in glioblastoma." (PMID 30558624, 2018). "The glutamate-cystine exchanger xCT (SLC7A11, system Xc−) is the main glutamate exporter in malignant brain tumors and as such a relevant drug target for treating deadly glioblastomas (WHO grades III and IV)." (PMID 28835855, 2017). "TAMs co-cultured with glioblastoma cells also exhibited a similar glutamatergic profile as freshly isolated TAMs except for a slight increase in SLC7A11 expression." (PMID 26047211, 2015). "Additionally, overexpression of γ-glutamyl transferase as well as xCT (SLC7A11) transporter in glioblastoma can maintain GSH homeostasis and protect tumor cells from oxidative stress." (PMID 41154707, 2025). "Finally, we validated, through western blot and flow cytometry, the role of SLC7A11 in inhibiting ferroptosis in glioblastoma." (PMID 38172959, 2024). "The upregulation of SLC7A11 in glioblastoma (GBM) leads to heightened levels of extracellular glutamate, facilitating the proliferation, activation, and suppressive capabilities of regulatory T (Treg) cells, consequently fostering intratumoral immunosuppression." (PMID 39040097, 2024). "Therefore, this study aimed to propose a new mechanism by which KCNA1 regulates the expression of SLC7A11 in glioblastoma." (PMID 38172959, 2024). "Consequently, ZDHHC8-mediated SLC7A11 stabilization fosters ferroptosis resistance during glioblastoma tumorigenesis." (PMID 39624080, 2024). "Additionally, we demonstrated for the first time that KCNA1 inhibits ferroptosis in glioblastoma by positively regulating the expression of SLC7A11." (PMID 38172959, 2024). "Interestingly, SLC7A11 expression has been found to be upregulated in glioblastoma cell lines and the brains of glioblastoma patients." (PMID 38739940, 2024). "Thus, the authors determined that the NF-κB inhibitor myrislignan drives the ferroptosis of glioblastoma cells through Slug–SLC7A11 signaling." (PMID 38539832, 2024). "In addition, although Cys2 uptake is essential for antioxidant protection of cancer cells against ferroptosis, Cys2 transport through SLC7A11 can also induce oxidative stress and cell death in glucose-deprived glioblastoma cells." (PMID 36072803, 2022). "NKAP protected glioblastoma cells from ferroptosis by positively regulating SLC7A11 expression." (PMID 35064112, 2022). "Overall, SIRT3 protects GBM cells from ferroptosis through mechanisms involving mitophagy and the regulation of SLC7A11, making it a promising therapeutic target in combination with ferroptosis induction for treating glioblastoma." (PMID 40710366, 2025).
glioblastoma (continued). "First, we compared glioblastoma and metastasis cells, and we could confirm that metastasis cell cultures expressed significantly less BCAT1, EAAT2 and SLC7A11 as compared to glioblastoma cells suggesting that these genes may represent a glioblastoma-typical gene profile." (PMID 30716120, 2019). "The downregulation of SLC7A11 increased ROS levels, decreased GSH levels, induced cell death, and reduced sensitivity to Temozolomide in U251 glioblastoma cells." (PMID 40000422, 2025). "Overexpression of SLC7A11 is a common occurrence in numerous cancers, including Glioblastoma (GBM)." (PMID 39993959, 2025). "However, METTL3 can also inhibit ferroptosis by downregulating SLC7A11 in lung cancer and glioblastoma (GBM)." (PMID 40271153, 2025). "Compared to lung cancer and glioblastoma (GBM), which often rely on SLC7A11 and GPX4 overexpression for ferroptosis evasion, HNC appears to exhibit distinct ferroptosis resistance patterns through Nrf2-mediated transcriptional upregulation of FSP1, HO-1, and lipid metabolic enzymes." (PMID 40867889, 2025). "It has been also described that NF-κB activation in glioblastoma cells by RSL3 treatment leads to an increase of lipid ROS and a reduction of anti-ferroptosis proteins such as GPX4, ATF4, and SLC7A11." (PMID 38539832, 2024). "In glioblastoma cells, forced NRF2 expression upregulates SLC7A11 (also known as xCT) and promotes ferroptosis resistance." (PMID 38424190, 2024). "In our study, we found that the positive expression of SLC7A11 and GPX4, which reduce phospholipid hydroperoxide and prevent ferroptosis, was decreased in U251 glioblastoma cells." (PMID 37582760, 2023). "To summarize, our study demonstrates that NeuroD4 overexpression can reprogram glioblastoma cells into neuron-like cells through the SLC7A11-GSH-GPX4 signaling pathway, thus offering a potential novel therapeutic approach for glioblastoma." (PMID 37582760, 2023). "Transcriptome profiling was performed using the TCGA clinical glioblastoma database (Public data, Project ID: TCGA-GBM, 166 glioblastoma cases) to investigate the correlation between NKAP and SLC7A11." (PMID 35064112, 2022). "Targeting of SLC7A11 combined with chemotherapy drugs can reduce the likelihood of cancer resistance and recurrence and improve the survival of patients with glioblastoma (GBM)." (PMID 31885621, 2019). "In glioblastoma and hepatocarcinoma, the expression level of SLC7A11 can be upregulated in an m6A-dependent manner with the assistance of METTL3 and IGF2BP1 via the inhibition of SLC7A11 mRNA degradation and increased SLC7A11 mRNA splicing and maturation." (PMID 41373022, 2025). "Especially, with respect to the xCT expression (SLC7A11), further investigations may reveal a higher correlation of the gene expression with glioblastoma." (PMID 38835368, 2024). "Indeed, knockdown of SLC7A11 elevated ROS and decreased GSH levels, as well as enhanced invasive properties of glioblastoma cells, while its overexpression not only increases resistance to oxidative stress and TMZ." (PMID 39259492, 2024). "The NF-κB pathway has been investigated in RSL3-induced ferroptosis in glioblastoma cells, in which it activated the NF-κB pathway, increased lipid ROS levels, and decreased the expression of ferroptosis-related proteins (GPX4, ATF4, and SLC7A11/xCT)." (PMID 38111578, 2023). "To investigate whether SLC7A11 and GPX4 inhibit NeuroD4-mediated neuronal reprogramming in glioblastoma cells, we co-overexpressed SLC7A11 and GPX4 along with NeuroD4." (PMID 37582760, 2023). "The expression level of SLC7A11 in biopsy tissues and glioma cell lines of patients with glioblastoma was higher than that in normal brain tissues; therefore, inhibition of system XC- or the GPx4 system by a FIN can enhance the RT effect in sarcoma, breast cancer and glioblastoma." (PMID 37007068, 2023).
glioblastoma (continued). "In addition, nutmeg inhibits glioblastoma (GBM) growth in a Slug-dependent manner through EMT-mediated ferroptosis, which inhibits NF-κB signaling activation by blocking p65 protein phosphorylation and induces ferroptosis through the Slug-SLC7A11 signaling pathway." (PMID 40143112, 2025). "Following 48 h of incubation with two different doses of anticonvulsants, significant effects could only be found in the expression of BCAT1, EAAT2 and GLUL in glioblastoma cells, whereas no changes in IDH1 and SLC7A11 expression were found." (PMID 30716120, 2019).
pancreatic cancer (60 papers, 2008 to 2026). "Furthermore, the authors verified this result with clinical data showing that low expression of miR‐139‐5p and high expression of SLC7A11 are associated with a poor prognosis, indicating that miR‐139‐5p may represent a new biomarker of pancreatic cancer." (PMID 33783998, 2021). "Integrating the results of PRNP silencing and pharmacological interventions, we conclude that PRNP exerts a critical ferroptosis-suppressing role in pancreatic cancer cells by positively regulating SLC7A11 and GPX4 protein expression." (PMID 41394830, 2025). "Overall, multidisciplinary approaches combining molecular biology, pharmacology, and clinical research are necessary to realize the therapeutic potential of targeting SLC7A11 in pancreatic fibrosis and pancreatic cancer." (PMID 40249927, 2025). "For example, researchers have revealed the potential of targeting SLC7A11 in pancreatic cancer treatment." (PMID 40012016, 2025). "In summary, solasonine inhibits the TFAP2A/OTUB1/SLC7A11 axis to stimulate ferroptosis and prevent the spread of pancreatic cancer cells." (PMID 40070365, 2025). "The findings suggest that LINC00578 mediates the inhibition of ferroptosis in pancreatic cancer by specifically interacting with UBE2K, thereby impeding the ubiquitination process of SLC7A11, and consequently fostering the progression of pancreatic cancer." (PMID 39827195, 2025). "It is worth noting that the existing results show that the knockout of Slc7a11 and Gpx4 in distinct mouse models of pancreatic cancer have different results in the process of pancreatic cancer." (PMID 39769097, 2024). "Overexpression of SLC7A11 has been shown to enhance pancreatic cancer proliferation, while downregulation reverses this effect." (PMID 38534987, 2024). "Our discovery that miR-485-3p targets SOX9 and SLC7A11 to inhibit stemness-like properties and gemcitabine resistance provides new insights into the regulation of hypoxia, CSCs, and chemoresistance in pancreatic cancer." (PMID 38811540, 2024). "SLC7A11, a cystine/glutamate antiporter, promotes pancreatic cancer proliferation through its role in glutathione biosynthesis." (PMID 38534987, 2024). "In the clinic, LINC00578 is closely associated with clinicopathologic factors and poor prognosis and correlated with SLC7A11 expression in pancreatic cancer." (PMID 36846713, 2023). "Then, we wondered how LINC00578 promotes SLC7A11 expression to inhibit ferroptosis in pancreatic cancer." (PMID 36846713, 2023). "Solasonine, a steroidal alkaloid, inhibits the TFAP2A/OTUB1-SLC7A11 axis, restores SLC7A11-reduced cell iron-related death, and inhibits pancreatic cancer cell progression." (PMID 37829798, 2023). "In pancreatic cancer, the cystine transporter SLC7A11 was identified as a druggable target downstream of the MCU-Nrf2 axis." (PMID 37829798, 2023). "Previous studies identified that SLC7A11 is necessary for the initiation and growth of primary pancreatic tumours and melanoma." (PMID 35804831, 2022). "Conditional knockout of SLC7A11 induces pancreatic cancer growth, in partly through cysteine depletion-induced ferroptosis." (PMID 36081847, 2022). "For example, we and others have observed that under cystine starvation conditions, pancreatic cancer cells upregulate SLC7A11 expression as a stress response." (PMID 35280777, 2022). "SLC7A11-positive macrophages were identified in lung, colon, ovarian, and pancreatic cancer patients, and these macrophages were mainly detected among SPP1 positive macrophage sub-clusters." (PMID 36470862, 2022). "To gain more evidence that the ceRNA network regulates ferroptosis in pancreatic cancer, we analyzed the relationship between the ceRNA axis and SLC7A11." (PMID 35795552, 2022). "In conclusion, solasonine is involved in ferroptosis by suppressing TFAP2A-mediated transcriptional upregulation of OTUB1, thereby activating ubiquitinated degradation of SLC7A11 and promoting pancreatic cancer cell ferroptosis." (PMID 35494004, 2022).